DIS3L2 (DIS3 like 3'-5' exoribonuclease 2)
Diseases named in the same sentence as DIS3L2 in open-access papers (continued):
Sharing a sentence is not in itself a finding about the gene and the disease.
cancer (17 papers, 2015 to 2025). A tumor composed of atypical neoplastic, often pleomorphic cells that invade other tissues. "In contrast, a clear loss in cancer related associations was observed upon KEGG pathway analysis of the transcripts downregulated in response to the triple knockdown (DIS3L2 + TUTs)." (PMID 37340282, 2023). "Some studies have associated DIS3L2 with tumorigenesis and cancer-related processes, however, its role in cancer development and progression is still unclear." (PMID 37340282, 2023). "DIS3L2, a conserved exoribonuclease, that plays a part in the degradation of cytoplasmic RNAs, is associated with several cancers." (PMID 33777092, 2021). "In addition, KEGG pathway enrichment from the pool of DIS3L2 KD downregulated transcripts displayed associations with various cancer and metastasis-associated pathways, which may reflect an oncogenic deceleration." (PMID 37340282, 2023). "Moreover, DIS3L2 is mutated in approximately 3–6% of carcinomas." (PMID 25879614, 2015). "The data suggested that YTHDF2 binds with m6A methylated GATA3 mRNA and recruits Dis3L2 to induce its degradation in cancer cells." (PMID 39800682, 2025). "DIS3L2 overexpression suppressed the growth of human cancer cell lines, and DIS3L2 knockdown increased cell growth." (PMID 38689093, 2024). "Nonetheless, the precise role of Dis3L2 in the progression of these diverse types of cancer is still incompletely understood." (PMID 35247037, 2023). "Collectively, these results contribute to improve our understanding of DIS3L2 function in key hallmarks of cancer and suggest a pro-tumorigenic role for this ribonuclease in advanced CRCs." (PMID 37340282, 2023). "Although other studies had described a role for DIS3L2 in sustaining cell viability in different cancer types, to our knowledge, this study is the first to demonstrate its critical role in enabling the invasive behavior of highly dedifferentiated CRC cells." (PMID 37340282, 2023). "In this cancer subtype, DIS3L2 mRNA and protein expression were upregulated in cancerous tissues versus matched adjacent noncancerous liver samples." (PMID 37340282, 2023). "To explore the clinical significance of DIS3L2 in cancer, we decided to investigate its gene expression across different tumorigenic tissues." (PMID 37340282, 2023). "Hereditary kidney cancer patients occupy 5–8% in all the diagnosed ones, and commonly harbor some cancer predisposition genes, such as TSC1/2, CDKN1C and DIS3L2." (PMID 34193180, 2021). "Knockdown of DIS3L2 enhanced the growth of human cancer cells, and overexpression prohibited these cells growth." (PMID 31924802, 2020). "DIS3 like 3'-5' exoribonuclease 2 (DIS3L2) has also been identified, among genes involved in cancer, cellular function and maintenance, and neurological disease, in a candidate region under selection in cattle." (PMID 30687385, 2018). "In addition, clustering analysis of expression profiles has shown that LIN28-positive cancer cells also display high expression of DIS3L2 and uridylation factors as well as miRNA let-7 targets." (PMID 37340282, 2023). "Altogether, these findings indicate that DIS3L2 could behave as tumor suppressor or tumor promotor depending on the cancer type." (PMID 37340282, 2023). "Most of the literature that concerns DIS3L2 characterizes its involvement in several RNA degradation pathways, however, there is some evidence that its dysregulated activity may contribute to cancer development." (PMID 37340282, 2023). "The DIS3 like 3’-5’ exoribonuclease 2 (DIS3L2), which is closely associated with the Lin28/let-7 pathway in several cancers, was shown to be downregulated by knockdown of lncRNA AC105461.1, which is located upstream of the DIS3L2 promoter, thereby enhancing the stemness of CRC." (PMID 35155247, 2022). "Interestingly, a recent study showed that Lin28B interacted with DIS3L2 in the cytoplasm of Lin28B-expressing cancer cell lines, suggesting that it was also involved in a TUTase-dependent pathway." (PMID 36008964, 2022).
cancer (continued). "Knockdown of Dis3l2 enhances the growth of human cancer cell lines." (PMID 29557542, 2019). "Moreover, gene ontology (GO) analysis of significant upregulated transcripts displays enrichment in mRNAs encoding proteins involved in cell cycle regulation and cancer-related pathways, which guided us to evaluate which specific hallmarks of cancer are differentially regulated by DIS3L2." (PMID 37340282, 2023). "However, the role of DIS3L2 in cancer is still poorly understood, namely whether it acts as a driver or suppressor of tumorigenesis." (PMID 37340282, 2023). "Given the inhibitory effect of DIS3L2 KD in cell viability, we explored a potential target of DIS3L2 among genes that clustered in the mTOR pathway, and we found AZGP1, whose mTOR inhibitory activity has been previously documented in different cancer types, including CRC." (PMID 37340282, 2023). "Altogether, these findings expand the knowledge on DIS3L2 role in cancer and suggests that, given its nearly absent effects in well-differentiated and non-transformed cells, the targeting of DIS3L2 may present a novel therapeutic venue to explore in advanced CRC." (PMID 37340282, 2023).
tumor (7 papers, 2014 to 2023). "Astuti and colleagues showed that the loss of DIS3L2 is associated with mitotic abnormalities and the abnormal expression of mitotic proteins, introducing the tumor suppressor activity of DIS3L2." (PMID 30057901, 2018). "RNA-seq gene expression data from tumor tissues and matched normal samples was used to evaluate DIS3L2 expression." (PMID 37340282, 2023). "The regressive tumor WT01 carried GLI3 Q1437*, the triphasic WT02 harbored MAX R60Q and MYCN T58M mutations, and the blastemal WT03 showed a heterozygous DIS3L2 deletion and a STK32C V339M mutation." (PMID 31562394, 2020). "In this study, the methylation status of five selected gene promoters (CDKN2A, hMLH1, MGMT, CSF2, and DIS3L2) confirmed the presence of DNA methylation in tumor tissues and matched normal tissues." (PMID 31924802, 2020). "DIS3L2 interacts with the heterogeneous nuclear ribonucleoprotein (hnRNP) U through its cold-shock domains and regulates the alternative splicing of the small GTPase RAC1’s pre-mRNA, yielding the production of the tumor-promoting splicing variant, RAC1B." (PMID 37340282, 2023). "However, there are several reports of tumor promoting roles for DIS3L2." (PMID 37340282, 2023).
infection (1 paper, 2020). The state of being infected such as from the introduction of a foreign agent such as serum, vaccine, antigenic substance or organism. "To determine if this mechanism is also sufficient to explain the loss of Pol II occupancy during MHV68 infection, we depleted Xrn1 and Dis3L2 individually or in tandem using siRNAs." (PMID 32032393, 2020). "The fact that knockdown of Xrn1 or Dis3L2 does not rescue Pol II occupancy during WT MHV68 infection indicates that either these mechanisms are redundant, or that the Pol II depletion phenotype is dominant." (PMID 32032393, 2020).
DIS3L2 also shares sentences with these, for which no sentence is quoted: neurological disease (2 papers); overgrowth syndrome (2); Beckwith-Wiedemann syndrome (1); cervical cancer (1); Denys-Drash syndrome (1); diabetes (1); hydrocephaly (1); Hypertension (1); inflammatory bowel disease (1); kidney tumour (1); Macrocephaly (1); Obesity (1); parasite infection (1); pulmonary diseases (1); Wilms’ tumour of the kidney (1).